AQP3 (aquaporin 3 (Gill blood group))
Diseases named in the same sentence as AQP3 in open-access papers (continued):
Sharing a sentence is not in itself a finding about the gene and the disease.
Sepsis (13 papers, 2018 to 2025). Sepsis is defined as life-threatening organ dysfunction caused by a dysregulated host response to infection. "We report for the first time that 30-day survival in sepsis patients was significantly associated with AQP3 (rs17553719) polymorphism genotypes." (PMID 38338680, 2024). "We demonstrate with this study that the C allele of the AQP3 rs17553719 polymorphism is associated with decreased 30-day survival in sepsis." (PMID 38338680, 2024). "In conclusion, the C allele of the AQP3 polymorphism (rs17553719) is associated with decreased survival in patients with severe sepsis." (PMID 38338680, 2024). "In summary, the C allele of the AQP3 polymorphism (rs17553719) shows an association with increased AQP3 expression and IL-33 concentration accompanied by decreased survival in patients with sepsis." (PMID 38338680, 2024). "There was an association between AQP3 polymorphism (rs17553719) and expression with survival outcomes in sepsis patients." (PMID 39544938, 2024). "Nevertheless, for the indication given, the study population was not small, and multivariate Cox regression analyses revealed AQP3 polymorphism (rs17553719) as an important and strong independent prognostic factor for 30-day survival in severe sepsis." (PMID 38338680, 2024). "The AQP3 polymorphism (rs17553719) exhibited an association with 30-day survival in patients with sepsis." (PMID 39768394, 2024). "Future studies are required to replicate these observations and unravel the precise molecular mechanism by which the C allele of the AQP3 polymorphism (rs17553719) influences survival in severe sepsis." (PMID 38338680, 2024). "The aim of this study is to investigate the polymorphism (rs17553719) and the expression of AQP3 in sepsis patients and correlate these measurements with the outcome of sepsis patients and the release of several cytokines." (PMID 38338680, 2024). "Thus, we investigated the polymorphism (rs17553719) and expression of aquaporin-3 (AQP3) and correlated these measurements with the survival of sepsis patients." (PMID 38338680, 2024). "Thus, the CC genotype of the AQP3 polymorphism represents an independent prognostic factor for survival in sepsis patients." (PMID 38338680, 2024). "The estimated hazard ratio of nearly 2 for the CC genotypes compared with the TT genotype suggests that the C allele of the AQP3 polymorphism may have important effects on AQP3 expression in sepsis." (PMID 38338680, 2024). "Furthermore, the AQP3 polymorphism represented an independent—and the most important—prognostic factor for survival in our sepsis patients." (PMID 38338680, 2024). "As we have also demonstrated in the past, a polymorphism in the AQP3 gene is associated with T-cell migration, and altered T-cell migration could play a role in sepsis patients." (PMID 38338680, 2024). "Here, we aim to investigate whether AQP3 promoter polymorphisms play a similar role and correlate with sepsis survival." (PMID 38338680, 2024). "Ziehe’s results showed that the increase in IL-33 concentration was positively correlated with the expression of aquaporin-3 (AQP3), accompanied by a shortened survival period in patients with sepsis." (PMID 39991638, 2024). "Altered expression of AQPs, such as AQP1, AQP3, and AQP5, correlates with sepsis severity, and polymorphisms in AQP5 have been linked to better survival rates and improved outcomes in sepsis-related acute respiratory distress syndrome (ARDS)." (PMID 39544938, 2024). "In our analysis, the AQP3 CC genotype was the strongest prognostic factor for sepsis lethality, with a hazard ratio of more than four in the multivariate model." (PMID 38338680, 2024). "The results verified tentatively that intestinal AQP3 expression plays an important role in protecting the intestine during sepsis." (PMID 38338680, 2024). "Previous studies in murine models of sepsis showed that the AQP3 expression level is downregulated after septic intestinal injury." (PMID 38338680, 2024).
Sepsis (continued). "Treatment with glycerol, which can substitute AQP3 function, can ameliorate the intestinal injury and improve sepsis survival." (PMID 38338680, 2024). "Results showed that the CC genotype was linked to decreased 30-day survival, higher AQP3 mRNA expression, and elevated IL-33 concentration, suggesting a potential role of AQP3 in sepsis prognosis." (PMID 39544938, 2024). "AQP3 mRNA expression increased over the duration of sepsis and was correlated with lymphocyte count." (PMID 38279209, 2024). "On the one hand, AQP3 protects the intestine, and, on the other hand, it damages pulmonary vascular permeability during sepsis." (PMID 38338680, 2024). "Another study also indicated that the expression levels of AQP3 and occludin were significantly reduced in intestinal mucosa of septic mice accompanied by an increase of plasma diamine oxidase concentration, indicating AQP3 might alleviate intestinal damage caused by sepsis." (PMID 38089478, 2023). "A recent study showed that Aquaporin 3 (Aqp3) is involved in the regulation of pulmonary vascular permeability and that antioxidants can reduce pulmonary permeability and downregulate the expression of Aqp3 in sepsis." (PMID 36465208, 2022). "Another study demonstrated that AQP3 participates in the regulation of pulmonary vascular permeability after sepsis, and the antioxidant Ss-31 has a protective effect on pulmonary vascular permeability by downregulating the expression of AQP3 and inhibiting reactive oxygen species production." (PMID 38338680, 2024). "Taken together, these results indicate that AQP9 or AQP3 could be novel drug targets in polymicrobial sepsis and valuable biomarkers of this worrisome condition." (PMID 38279209, 2024). "In THP-1 monocytic cells, AQP3 is implicated in IL-6, pro-IL-1β, and TNFα transcription via TLR4 engagement upon LPS priming, and the activation of the NLRP3 inflammasome, known to be upregulated in sepsis, is influenced by AQP3 expression." (PMID 39125952, 2024). "However, the precise mechanisms through which AQP3 affects the production of inflammatory cytokines in sepsis have to be elucidated." (PMID 38279209, 2024). "However, in contrast to AQP3, the expression of which increases over the duration of sepsis, AQP9 expression seems to be unaltered." (PMID 38279209, 2024). "An AQP3 increase in macrophages is associated with survival, while AQP9 in neutrophils is inhibited during a prolonged inflammatory state and its expression was considered an independent risk factor for sepsis lethality." (PMID 39125952, 2024). "It seems that AQP3 has different effects depending on the tissue in sepsis." (PMID 38338680, 2024). "Finally, in a gene expression analysis of five critically ill patients who developed sepsis and septic shock, AQP3 was found downregulated." (PMID 39768394, 2024). "In addition, AQP3 seems to be involved in the formation of the inflammasome, which is important in sepsis pathophysiology." (PMID 38338680, 2024). "Furthermore, the CC genotype of AQP3 is accompanied by a higher expression of AQP3 and IL-33 in sepsis." (PMID 38338680, 2024). "Furthermore, the antioxidant Ss-31 was observed to reduce AQP3 expression and ROS levels, thereby improving vascular permeability and enhancing the survival of rats with sepsis." (PMID 39544938, 2024). "Moreover, AQP3 seemed to improve the outcome in a sepsis mouse model." (PMID 38338680, 2024). "In addition to lung function, AQP3 might also play a role in the stroma and the kidneys during sepsis." (PMID 38279209, 2024). "Considering our data, AQP3 may be another important player in immune cells during sepsis." (PMID 38279209, 2024). "The reduced expression of AQP3 during sepsis might play a role in immune cell migration." (PMID 37143707, 2023). "However, it is unclear whether AQP3 has an impact on the outcome of sepsis patients." (PMID 38338680, 2024).
Sepsis (continued). "Recently, AQP3 and AQP9, the most representative AQPs in macrophages and neutrophils, respectively, were shown to respond differently in the sepsis clinical condition." (PMID 39125952, 2024). "Therefore, our results may suggest an opposing role for AQP9 and other AQPs like AQP3 in sepsis." (PMID 38279209, 2024). "Recent studies suggest that AQPs, particularly aquaglyceroporins like AQP3, AQP7, AQP9, and AQP10, play pivotal roles in immune cell metabolism and offer new therapeutic avenues for sepsis treatment." (PMID 39544938, 2024). "Hence, AQP3 expression might have a potential relevance in sepsis." (PMID 38338680, 2024). "AQP3 and AQP4 have been found to promote sepsis development, with their suppression proving to be beneficial for the experimental models." (PMID 38203657, 2023). "Several studies showed that AQP3 is essential for T cell function and macrophage migration and that AQP5 and AQP9 regulate neutrophil cell migration and impact sepsis survival." (PMID 29449936, 2018). "High levels of AQP3 were associated with augmented survival, whereas AQP9 did not appear to change during sepsis when normalized against the neutrophil count, and a low expression of AQP9 was associated with increased survival." (PMID 40558507, 2025). "The main finding of our study is the correlation between AQP3 and AQP9 expression and sepsis survival at day 8, suggesting AQP modulation might be a promising therapeutical approach during sepsis." (PMID 38279209, 2024). "Additionally, elevated levels of O-GlcNAcylation, a post-translational modification of proteins that occurs during sepsis, further increase glucose uptake via GLUT1 and regulate glycerol transport through AQP3." (PMID 39544938, 2024). "This underscores the potential relevance of AQP3 expression in severe sepsis, regardless of the mechanisms involved." (PMID 38338680, 2024). "AQP3 (p < 0.0001) expression more than doubled when comparing day 8 of sepsis with day 1, whereas AQP9 mRNA expression was not altered over the duration of sepsis." (PMID 38279209, 2024). "In conclusion, AQP3 and AQP9 may play contrary roles in the pathophysiology of sepsis, and these results suggest that AQP9 may be a novel drug target in sepsis and, concurrently, a valuable biomarker of the disease." (PMID 38279209, 2024). "Thus, the roles of AQP3 and AQP9 differ in the pathophysiology of sepsis and may be useful biomarkers for sepsis." (PMID 39768394, 2024). "However, aquaporin-3 (AQP3) could be of special interest, as it was demonstrated that AQP3 participates in the regulation of pulmonary and intestinal function as well as immune cells in sepsis." (PMID 38338680, 2024).
lung adenocarcinoma (12 papers, 2018 to 2026). A carcinoma that arises from the lung and is characterized by the presence of malignant glandular epithelial cells. "Aquaporin 3 (AQP3), which is mostly expressed in pulmonary epithelial cells, was linked to lung adenocarcinoma (LUAD)." (PMID 39060229, 2024). "AQP3 seem to be implicated into tumor differentiation and processes related to clinical stage in lung adenocarcinomas." (PMID 29503618, 2018). "Gene expression profiling revealed that AQP3 was markedly upregulated in lung adenocarcinoma tissue." (PMID 39611488, 2025). "The Aqp3 knockout mice model displayed slower urethane-induced lung adenocarcinoma formation, reduced tumor proliferative activity and glucose metabolism, and weaker M2 macrophage polarization." (PMID 39060229, 2024). "Recent studies indicate that in lung adenocarcinoma, higher AQP3 transcript levels in cancer tissues were related to poor prognosis, and silencing of AQP3 decreased H2O2-induced proliferation." (PMID 34829727, 2021). "Levels of AQP3 in lung adenocarcinoma were correlated with tumor differentiation and clinical stage." (PMID 32679804, 2020). "AQP3 has a potential interaction relationship with PPAR-γ and NF-κB in the microenvironment of lung adenocarcinoma." (PMID 39060229, 2024). "Recently, compared with non-neoplastic lung tissue, a notably high expression of AQP3 was found in lung adenocarcinoma samples." (PMID 39611488, 2025). "Therefore, we aimed to investigate how AQP3 and AQP4 protein expression in lung adenocarcinoma (ADC) biopsy samples correlate with clinical and pathological parameters." (PMID 36233821, 2022). "On this regard, the specific distribution of various AQPs in lung adenocarcinoma (AQP1, AQP3, and AQP5) has suggested that these proteins could be involved in different and distinct aspects of the cancerous process." (PMID 29503618, 2018).
ovarian carcinoma (11 papers, 2013 to 2025). A malignant neoplasm originating from the surface ovarian epithelium. "Increased AQP3 protein in ovarian cancer cells was associated with EGF-stimulated growth and migration, blocked by the natural product curcumin." (PMID 33499000, 2021). "Intriguingly, our study found that AQP3 mRNA expression significantly associated with better prognosis in all ovarian cancer patients, both in endometrioid and serous types ovarian cancer patients." (PMID 29472315, 2018). "Another study suggested that AQP3, regulated by estrogen, might be adopted as a diagnostic biomarker for the early detection of ovarian cancer." (PMID 35972604, 2022). "AQP3 upregulation by EGF promoted cell migration in an ovarian cancer cell line, which was inhibited by curcumin." (PMID 32679804, 2020). "Overexpression of AQP3, AQP6/2L, and AQP11 were associated with favorable OS in grade III ovarian cancer patients." (PMID 29472315, 2018). "CURC treatment was also found to downregulate AQP1 in rat choroid plexus cells, useful to reduce cerebrospinal fluid production in some pathophysiological conditions, and AQP3 expression in human ovarian cancer cells." (PMID 29292793, 2017). "In addition, curcumin inhibits EGF-induced AQP3 upregulation, impairing ovarian cancer cell migration." (PMID 39941100, 2025). "AQP3 mRNA expression was significantly correlated with better OS for all ovarian cancer patients, HR = 0.77 (0.67–0.89), P=0.00043, serous ovarian cancer patients, HR = 0.82 (0.7–0.95), P=0.01, and endometrioid ovarian cancer patients, HR = 0.15 (0.03–0.93), P=0.019." (PMID 29472315, 2018). "Also in this context, curcumin (or a stable analog) proposed for therapeutic treatment of ovarian cancer, downregulated AQP3 and reduced cell migration in CaOV3, an effect mediated by inhibition of EGFR signaling." (PMID 29721498, 2018). "AQP3 is also upregulated by estrogen, being implicated in the stimulation of cell migration and invasion in ER-positive breast cancer cells through the modulation of EMT-related factors and the reorganization of the actin cytoskeleton and in the development of the chicken oviduct and ovarian cancer." (PMID 39941100, 2025). "Curcumin was found to inhibit EGF-induced upregulation of AQP3 and migration in human ovarian cancer cells, via inhibition of AKT/ERK and PI3K pathways; however, curcumin affects a number of biochemical pathways and might not be suited when AQP-specific modulation is required." (PMID 29922644, 2018). "Moreover, overexpression of AQP3 mRNA speculated favorable OS in poor differentiation and advanced clinical stage ovarian cancer patients." (PMID 29472315, 2018). "Curcumin, which regulates AQP3 gating, exerted an inhibitory effect on EGF-induced AQP3 upregulation and ovarian cancer cell migration through the PI3K/Akt and MEK/ERK pathways." (PMID 35972604, 2022). "Metal-based inhibitors that have been tested in models of cancer include AQP3 inhibitors such as NiCl2 and CuSO4, which inhibited EGF-induced cell migration in human ovarian cancer cells." (PMID 29922644, 2018). "Our results revealed that higher AQP0, AQP1, and AQP4 mRNA expression were correlated with poor OS, whereas higher AQP3, AQP5, AQP6, AQP8, AQP10, and AQP11 showed better OS in ovarian cancer patients." (PMID 29472315, 2018). "Taken together, our results indicated that high level of AQP3 and AQP5 might favor clinical outcomes in ovarian cancer." (PMID 29472315, 2018). "Intriguingly, when concurrent (Platin + Taxol) treatment and prognostic significance were analyzed, the data showed that high expression of AQP0 and AQP1 mRNA were correlated to decrease survival rate and high expression of AQP3, AQP6, and AQP11 were correlated to good OS in ovarian cancer patients." (PMID 29472315, 2018).
ovarian carcinoma (continued). "Additionally, AQP3, AQP6, and AQP11 mRNA expression were correlated with better OS, whereas AQP0 and AQP1 showed poor OS in all ovarian cancer patients treated with Platin, Taxol, and Taxol + Platin chemotherapy." (PMID 29472315, 2018). "However, there is no publication reporting on the prognostic significance of AQP3 in human ovarian cancer." (PMID 29472315, 2018).
Obesity (9 papers, 2013 to 2026). Accumulation of substantial excess body fat. "In addition, obesity has been associated with increased AQP3 and AQP9 expression and decreased AQP7 expression in human subcutaneous adipose tissue." (PMID 29186031, 2017). "Interestingly, in human subcutaneous adipose tissue, obesity is associated with increased AQP3 and AQP9 expression and decreased AQP7 expression." (PMID 29186031, 2017). "In vivo experiments, macrophage-specific AQP3 conditional knockout mice exhibit reduced weight gain and adipose tissue inflammation in a high-fat diet-induced obesity model." (PMID 41981083, 2026). "Overall, additional studies will be needed to shed light on the role of perilipin-1 on AQP3 functionality under physiological conditions and metabolic diseases, such as obesity." (PMID 36077012, 2022). "Thus, altered expression of AQP3 and desmosomal molecules in HFD-fed mice appears to be a secondary consequence of other metabolic or biochemical changes associated with obesity." (PMID 31581253, 2019). "In fact, although all aquaglyceroporins (AQP3, 7, 9, and 10) are expressed in human adipose tissue, AQP7 expression increases along with white adipocyte differentiation and has been reported to be involved in obesity." (PMID 31963489, 2020). "Leptin deficiency was associated with obesity and NAFLD exhibiting an AQP3 and AQP7 increase in WAT, without changes in hepatic AQP9." (PMID 26159457, 2015). "In conclusion, the present study demonstrates on one hand the expression of AQP7 in human adipocyte plasma membrane and on the other hand the presence of an alternative glycerol channel, AQP10, that working with AQP3 and AQP7 ensures glycerol exit from adipocyte, thus protecting humans from obesity." (PMID 23382902, 2013). "AQP3 activators may exert therapeutic effects on defects in the hydration, lubrication, and proliferation of the skin, bladder, vagina, and respiratory system, whereas AQP7 activators may be applicable as useful adjuvants for obesity treatment." (PMID 39195451, 2024).